AFP (alpha fetoprotein)
Diseases named in the same sentence as AFP in open-access papers (continued):
Sharing a sentence is not in itself a finding about the gene and the disease.
Cirrhosis (continued). "Intriguingly, AFP failed to exhibit significance in predicting the prognosis of compensated cirrhosis.While the literature lacks a unanimous consensus on AFP's utility in HCC, it appears that relying solely on AFP for determining overall prognosis might be suboptimal." (PMID 38374854, 2024). "Thus, in the future study about predicting early recurrence of AFP‐negative HCC patients with cirrhosis after liver resection, evaluation of liver function may be essential." (PMID 38130028, 2023). "An AFP cutoff of 20 ng/mL provided a sensitivity of ~60% and a specificity of ~90%, although the optimal cutoff might be lower in those with nonviral etiologies of cirrhosis." (PMID 37627125, 2023). "However, approximately 32–59% of patients with HCC have normal AFP levels; moreover, non-tumor-related AFP elevations may occur in patients with cirrhosis or chronic hepatitis, making AFP an inappropriate marker in surveillance." (PMID 35454929, 2022). "The result of this study is that the combination of AFP + PIVKA-II biomarkers demonstrated the best performance and represented the highest diagnostic efficacy in detecting HCV-induced HCC, regardless of the presence or the absence of HCV-induced cirrhosis and the BCLC/TNM staging." (PMID 36079006, 2022). "AFP >92 ng/mL and positive MVI were associated with a worse prognosis, regardless of whether the patient has cirrhosis, while HBsAg positivity was associated with a poorer prognosis in rHCC patients with cirrhosis, and it did not affect the prognosis of rHCC patients without cirrhosis." (PMID 35342424, 2022). "In addition, AFP may also be elevated in some benign liver diseases, such as chronic hepatitis and cirrhosis even in the absence of HCC." (PMID 36263214, 2022). "In addition, AFP may be elevated in some benign liver diseases, such as chronic hepatitis and cirrhosis without HCC." (PMID 36119529, 2022). "However, about 30% to 40% of patients diagnosed with liver cancer have no significant increase in AFP, and the sensitivity of AFP in early-stage liver cancer is only 30% to 40%, while about 20% to 50% of patients with chronic hepatitis and cirrhosis have elevated AFP." (PMID 36523478, 2022). "However, the use of AFP alone is limited since not all HCC cells that secrete AFP and AFP may be elevated in cirrhosis or hepatitis." (PMID 33477833, 2021). "Thus, HAN253WTLTPLK (H5N4S2) and (H5N4S1) may be useful in distinguishing AFP-negative HCC from cirrhosis." (PMID 33889548, 2021). "Notably, the upregulation of Sphingosine (d18:1)-1-P could also distinguish AFP-negative HCC from cirrhosis with an AUC of 0.79." (PMID 33014866, 2020). "Thus, AFP combination of ALT, AST, and NLR was superior to any single indicator or any combinations of each biomarkers, except in the CHB patients without cirrhosis group, and displayed a good diagnostic performance for detecting HBV‐HCC among almost all subgroups." (PMID 32150664, 2020). "However, the sensitivity and specificity of AFP levels were not sufficient for HCC diagnosis, as patients with cirrhosis and chronic hepatitis could show elevated AFP levels." (PMID 31602270, 2019). "However, AFP, cirrhosis and Child-Pugh system were not correlated with 5-HT and YAP/VGLL4 ratio." (PMID 29950605, 2018). "Interestingly, our study further revealed a high diagnostic accuracy for the detection of HCC even in AFP-negative cases (AUC=0.790; sensitivity 71.0% and specificity 83.0%) when comparing all AFP-negative HCC patients (cut-off < 20 ng/mL AFP) with AFP-negative fibrosis/cirrhosis (F1-F4) patients." (PMID 28526812, 2017). "In our study, the combination of AFP (cut-off of ≥ 20 ng/mL) and sAxl at a cutoff of ≥ 61 ng/mL reached excellent diagnostic accuracy with a sensitivity and specificity of 84.0% and 100% for HCC with cirrhosis (AUC 0.954), and 85.7% and 96.4% for HCC without cirrhosis (AUC 0.941), respectively." (PMID 28526812, 2017).
Cirrhosis (continued). "Interestingly, when NASH-related HCC was compared to NASH cirrhosis, MDK had a greater AUROC (0.86; 95% CI 0.72–1.0) compared to AFP (0.76; 95% CI 0.58–0.95) and OPN (0.66; 95% CI 0.44–0.88), suggesting that MDK may have a role in the diagnosis of NASH-related HCC." (PMID 27219517, 2016). "AST, ALT, albumin, platelet count, prothrombin time, hyaluronic acid, AFP, and PIVKA-II that were associated with cirrhosis by univariate analyses were excluded because they were apparently the result of cirrhosis but not the causes for the progression to cirrhosis." (PMID 25713769, 2015). "PHA typically arises in a non-cirrhotic liver and does not elevate AFP, whereas HCC often develops in cirrhosis and shows increased AFP levels." (PMID 41594267, 2026). "This study was designed to evaluate the role of PIVKA-II as a diagnostic marker of HCC by comparing serum levels of PIVKA-II and alpha-fetoprotein (AFP) in HCC patients and in two control groups, patients with chronic liver disease and cirrhosis without HCC." (PMID 39857948, 2025). "In patients with cirrhosis, even after achieving SVR 12, an abdominal ultrasound with or without alpha fetoprotein (AFP) measurement every 6 months and upper endoscopy every 2–3 years is recommended for life." (PMID 40649175, 2025). "All AUCs of circ-0028861 were approximately 0.80 in differentiating between HBV-HCC, small HBV-HCC, early HBV-HCC, and AFP-negative HBV-HCC from hepatitis B infection and HBV-cirrhosis." (PMID 40584295, 2025). "The risk factors for overall mortality and liver-specific mortality are old age, cirrhosis, larger tumor size, higher TNM staging, higher serum AFP level and anemia, irrespective of the presence of AD." (PMID 39031214, 2024). "However, a few non-HCC conditions, including hepatic cirrhosis, may lead to the elevation of AFP." (PMID 38537933, 2024). "For 120 patients with nonviral cirrhosis, including 62 HCC (23 early-stage) patients, LC-SPIK had an AUC of 0.84, while AFP had an AUC of only 0.72." (PMID 38611638, 2024). "On the other hand, in patients with early-stage HCC and negative AFP, MDK had better performance compared with AFP for distinguishing early-stage HCC and small-sized tumors from non-HCC cases, including cirrhosis." (PMID 38247828, 2024). "There is consensus among professional societies that patients with cirrhosis should undergo ongoing HCC surveillance, using a 6-month ultrasound scan (US) with or without AFP testing, after achieving SVR." (PMID 39319076, 2024). "Compared to non-MAFLD tumours, M-MAFLD tended to occur on less advanced cirrhosis by MELD score > 10 or significant portal hypertension, as well as being older, having poorer performance status (ECOG > 0) and lower AFP." (PMID 37470858, 2023). "In the clinical setting, the most difficult part of diagnosing AFP-negative HCC is excluding patients with hepatitis and cirrhosis." (PMID 36890811, 2023). "EASL recommends semi-annual abdominal ultrasound exams, without determination of serum AFP level, not only for HCV patients with cirrhosis but also for those with the METAVIR F3 stage of fibrosis." (PMID 37762706, 2023). "The international guidelines suggest performing a 6 months surveillance with a US, with or without AFP measurements, in all patients with liver cirrhosis and in a subgroup of patients with HBV chronic infection without cirrhosis." (PMID 36831120, 2023). "In a population-based cluster-randomized study from China, surveillance with AFP and USG reduced HCC-related mortality compared with no surveillance in patients with chronic HBV infection with or without cirrhosis." (PMID 37568696, 2023). "Small tumor size; female sex; lack of cirrhosis; BCLC stage 0; high expression of APOL2, APOL3 and APOL6; and low AFP levels indicated higher survival rate in the GSE14520 cohort." (PMID 38017264, 2023).
Cirrhosis (continued). "The exLR-based HCC classifier has utility beyond AFP, not only for diagnosing early-stage or AFP-negative HCC, but also for distinguishing HCC patients from those with hepatitis, cirrhosis, or benign tumors." (PMID 37006626, 2023). "The studies did not perform an in-depth study analysis of the diagnosis of AFP-negative HCC, so our current study examined the differences in the expression of GGT in diverse populations (healthy individuals, hepatitis, cirrhosis, and HCC)." (PMID 36890811, 2023). "The levels of AST, ALT, CHE, Fib, eGFR, FBG, serum Na, PLT, AFP, and HBV-DNA were significantly lower in the cirrhosis group compared with the non-cirrhosis group (P < 0.001)." (PMID 35366805, 2022). "AFP and D-bilirubin were independent predictors of RFS, and AFP was an independent predictor of OS in all rHCC patients without cirrhosis." (PMID 35342424, 2022). "In the present study, we observed a good diagnostic accuracy of serum LC-SPIK for the detection of HCC in patients with NAFLD cirrhosis; the biomarker exhibited considerable performance even in early-stage HCC and in patients with false-negative AFP results." (PMID 36005169, 2022). "One study mentioned that HCC patients with negative AFP tended to be older males with less HBV infection, more non-viral etiology, and less cirrhosis." (PMID 35461226, 2022). "Third, although the COSSH ACLF scoring system exhibited a good predictive ability (C-index = 0.762) for HBV-ACLF in our study, it does not include the variables of Na, AFP, HBV DNA, and the PreLD (cirrhosis or chronic hepatitis)." (PMID 34222294, 2021). "Semiannual ultrasound (US) with or without measurement of alpha fetoprotein (AFP) is recommended as the first-line screening test for HCC across all etiologies of liver disease and cirrhosis." (PMID 36090909, 2021). "The independent predictors of OS (cirrhosis, gamma-glutamyl transpeptidase (GGT), tumor differentiation and CNLC staging system) and RFS (α-fetoprotein (AFP) and CNLC staging system) were incorporated into the two nomograms." (PMID 35127471, 2021). "We investigated the serum sphingolipid profile in patients with HCC or cirrhosis and explored the potential diagnostic efficiency of serum sphingolipid metabolites which may be helpful in differentiating HCC including α-fetoprotein (AFP)-negative HCC from cirrhosis." (PMID 33014866, 2020). "Average serum AFP in patients with HCV infection and compensated cirrhosis without HCC was 9.4 ng/ml and ranged between 0.5 ÷ 406 ng/ml." (PMID 32341704, 2020). "In this study, we found that 10 sphingolipids (2 Cer, 1 C1P, 2 HexCer, 1 dhSph, 1 dhS1P, 1 dhC1P, 1 HexSph, 1 S1P) including Sphingosine (d18:1)-1-P exhibit significant difference between HCC or AFP-negative HCC and cirrhosis." (PMID 33014866, 2020). "For diagnostic accuracy, PTX3 exhibited higher AUC, sensitivity, and specificity than did AFP in HCC patients in relation to chronic hepatitis, cirrhosis and chronic HBV infection without HCC." (PMID 33219288, 2020). "The difference in baseline clinical parameters was not significant between AFP-negative HCC and cirrhosis." (PMID 33014866, 2020). "This also addressed a problem, approximately 35% of patients with HCC were AFP negative, and elevated AFP concentration was also observed in non-HCC patients and patients with chronic hepatitis or cirrhosis." (PMID 32610709, 2020). "Previous studies reported the stratification of HCC incidence by FIB-4 scores and AFP levels after SVR and by scores composed of patient sex and age, with and without cirrhosis." (PMID 33284844, 2020). "The level of AFP in cirrhotic patients was remarkably lower than that in HCC (P < 0.01, Mann–Whitney U test), whereas the difference of AFP level between cirrhosis and AFP-negative HCC was not significant (P > 0.05, Mann–Whitney U test)." (PMID 33014866, 2020). "A total of 72 HCC patients, including 24 serum AFP-negative HCC patients, and 104 patients with cirrhosis were included in the present analysis." (PMID 33014866, 2020).
Cirrhosis (continued). "Spearman rank correlation analysis revealed that serum Sphingosine (d18:1)-1-P was not correlated with AFP in patients with cirrhosis, AFP-positive HCC, and AFP-negative HCC." (PMID 33014866, 2020). "In particular, PTX3 levels were highly discriminative of AFP-negative (≤ 20 ng/mL) and early-stage HCC from chronic hepatitis, cirrhosis and chronic HBV infection without HCC." (PMID 33219288, 2020). "However, not all HCCs secrete AFP, and AFP may be elevated in cirrhosis or hepatitis cases." (PMID 32923383, 2020). "Through subgroup analysis, we found that antiviral therapy significantly reduced AFP in HBV‐HCC patients with HBeAg+, as well as, in the HBV‐HCC patients with cirrhosis compare to patients without these factors." (PMID 32150664, 2020). "A total of 574 patients with cirrhosis, including 288 LCC (124 AFP-negative) and 286 LC patients, were recruited into the present study." (PMID 32038998, 2019). "HCC patients had higher α-fetoprotein (AFP) levels than liver cirrhosis patients (p < 0.05), and among HCC patients those who have cirrhosis also had higher AFP levels than those who do not have." (PMID 29435160, 2018). "AASLD recommends that patients with NAFLD cirrhosis should be considered for HCC screening with ultrasound testing and with or without measurement of blood alpha-fetoprotein (AFP) levels, every 6 months." (PMID 30065915, 2018). "In discriminating HCC without cirrhosis from LC, the AUC of DCP (0.871, 95% CI 0.828–0.915) was much better than that of AFP (0.711, 95% CI 0.647–0.774), and the combination of the two markers had a similar AUC (0.875, 95% CI 0.831–0.919)." (PMID 27070780, 2016). "We found no positive correlation with age, gender, HBV infection, cirrhosis, ALT, AFP, and vascular invasion." (PMID 26540343, 2015). "Although serum alpha-fetoprotein (AFP) is not currently recommended as a diagnosis marker for HCC, in patients with cirrhosis or chronic hepatitis B, AFP is an important indicator of diagnosis and prediction for HCC occurrence." (PMID 26093084, 2015). "By multivariate logistic regression analysis, hepatic cirrhosis was attained independent of higher APRI, no fatty change of the liver on US findings, higher BMI and higher AFP levels." (PMID 24349054, 2013). "Patients: HCC vs. (cirrhosis and healthy)Tests: methods for serum GOLPH2 and AFP not reported.Letter; no usable data." (PMID 22244200, 2012). "For the main guidelines analysis, we estimated the health benefits and economic impacts of 6-monthly HCC surveillance with US, with or without AFP testing, versus no routine HCC surveillance as the comparator (status quo for people with cirrhosis in Australia15)." (PMID 40584144, 2025). "Although AFP is not included in non‐invasive indexes, it had a remarkable contribution in predicting cirrhosis, in addition to platelet, GGT, age, and PT features known to be important in predicting cirrhosis in CHC patients." (PMID 40384539, 2025). "Furthermore, the AUCs of circ-0028861 plus AFP (0.91, 0.82, and 0.86, respectively) were higher than those of AFP (0.82, 0.69, and 0.76, respectively) for distinguishing HBV-HCC from chronic HBV infection, HBV without cirrhosis, and hepatitis B with cirrhosis." (PMID 40584295, 2025). "Importantly, PTX3 levels were especially effective in identifying α-fetoprotein (AFP)-negative and early-stage HCC, distinguishing it from chronic hepatitis, cirrhosis, and chronic HBV infection without HCC." (PMID 41462970, 2025). "The possible reason is that AFP is not a specific marker for HCC, and it can also be elevated to varying degrees in a variety of conditions, such as germ cell tumours, other gastrointestinal tumours, or cirrhosis." (PMID 38281008, 2024). "Given current technologies, patients without cirrhosis who do not meet AASLD criteria for HCC surveillance, which entails abdominal ultrasound every 6 months, might benefit from serial AFP measurement." (PMID 37078924, 2023).
Cirrhosis (continued). "A microsimulation model was used to evaluate three strategies: biannual ultrasound, biannual ultrasound with alpha-fetoprotein (AFP) and no formal surveillance for patients having one of the conditions: non-cirrhotic CHB, compensated cirrhosis or decompensated cirrhosis." (PMID 37076870, 2023). "Similarly, gender, tumor size ≤5cm, without HBV/HCV infection, none of cirrhosis, low or middle level differentiation, positive MVI, and AFP<400 appeared to influence the advantages of neo-adjuvant therapy on PFS, but again without statistical significance." (PMID 36923427, 2023). "In patients with chronic HCV infection, AFP may be elevated in the absence of HCC, especially in patients with advanced fibrosis or cirrhosis." (PMID 37078924, 2023). "We first recruited 27 early-stage primary HCC patients, of whom 8 patients had serum AFP ≤ 7 ng/mL, and then we additionally recruited 15 HCs, 19 HBV-related cirrhosis patients, 11 CHB patents (without cirrhosis), and 24 early-stage primary HCC patients with serum AFP ≤ 7 ng/mL." (PMID 36421714, 2022). "For non-antiviral group, the abnormal percentage of AFP levels were lower in patients with AST ≤ 1× ULN than in patients with AST > 1× ULN in the CHB, cirrhosis, and early-stage HCC subgroups (8.7% vs. 46.0%, p < 0.001; 15.6% vs. 58.2%, p < 0.001; and 58.1% vs. 76.1%, p < 0.001, respectively)." (PMID 36016291, 2022). "Untreated or chronically undertreated FAH−/− adult pigs (No. 266, prior experiment) develop cirrhosis, adenomas, and ultimately HCC at 12 months, as shown here with hepatocellular morphological derangement, extensive stage 4 fibrosis, and significant AFP staining (right column)." (PMID 36008405, 2022). "Hence, we chose to use an ROC curve to determine the cutoff value, and we evaluated the relationship between AFP and the OS and RFS in rHCC patients with or without cirrhosis." (PMID 35342424, 2022). "Alpha-fetoprotein (AFP) is considered the most commonly used tumor marker for the identification and monitoring of HCC, but it is of low specificity and elevated also in non-cancer liver diseases such cirrhosis and chronic hepatitis." (PMID 36672564, 2022). "First, some basic parameters of the cirrhosis patients from GSE15654, such as age, gender, especially AFP level were missing, so we could not further perform a comparative analysis of predictive value between the risk signature and AFP." (PMID 34335764, 2021). "The algorithm was better than AFP alone in HCC detection in the six months prior to clinical diagnosis (sensitivity 53%; 10% false-positive rate) but requires validation in other nonviral etiologies of cirrhosis." (PMID 34754704, 2021). "In conclusion, upregulation of serum Sphingosine (d18:1)-1-P may potentially help to differentiate HCC, including AFP-negative HCC, from cirrhosis." (PMID 33014866, 2020). "Finally, elderliness, male, cirrhosis, HBeAg+, or no‐antiviral therapy, and elevation of ALT, AST, neutrophil‐lymphocyte ratio (NLR), and AFP were all be independent predictors of HBV‐HCC occurring in these CHB patients." (PMID 32150664, 2020). "Serum alpha-fetoprotein (AFP) levels were significantly higher in patients with HCC than in healthy controls, but the AFP levels could not distinguish tumor size or cirrhosis in HCC patients." (PMID 33225985, 2020). "In addition, AFP can be affected by many non-HCC diseases (such as hepatitis, cirrhosis, cholangiocarcinoma, and so on)." (PMID 33014866, 2020). "The serum AFP level may not be reliable for the detection of HCC in the early stages; moreover, it appears to be more inaccurate among patients with cirrhosis." (PMID 31590436, 2019). "However the specificity and sensitivity of AFP used in liver cancer screening are not satisfactory, although it is useful in HCC surveillance in patients with cirrhosis." (PMID 29268718, 2017).